IL21 (interleukin 21)
Diseases named in the same sentence as IL21 in open-access papers (continued):
Sharing a sentence is not in itself a finding about the gene and the disease.
parasitemia (continued). "However, in stark contrast to WT mice, they developed sustained high parasitemias during the chronic phase of infection (e.g., parasitemias of 17% in Il21-/- and 23% in Il21r-/- mice compared with less than 0.04% in WT C57BL/6 at day 36 post-infection)." (PMID 25763578, 2015). "Mice deficient either in IL-21 or the IL-21 receptor fail to resolve the chronic phase of P. chabaudi infection and P. yoelii infection resulting in sustained high parasitemias, and are not immune to re-infection." (PMID 25763578, 2015). "Despite the tissue distribution and the omnipresence of IL-21 target cells in tissues in which protozoan and helminth parasites reside, the role of the IL-21/IL-21R signaling pathway in protection against and/or the promotion of inflammation during parasitic infections is not fully understood." (PMID 31867283, 2019). "To investigate if parasite burdens were associated with specific cytokines, we performed a correlation analysis comparing parasitemia and cardiac parasite burden with the TH17 cytokines IL-17A, IL-21, IL-22, and IL-23." (PMID 33547365, 2021). "Hence, the IL-21 has also demonstrated an important role during this process since the IL-21 KO mice showed decreased numbers of splenic GC B cells and ASCs in the bone marrow, lower antibody titers, and, consequently, a failure to control the parasitemia levels upon challenge." (PMID 30619319, 2018). "Similar to Il21-/- and Il21r-/- mice, mixed BM chimeric mice bearing Il21-/- T cells failed to control the chronic phase of infection and showed increasingly and sustained high parasitemias during this phase of infection." (PMID 25763578, 2015). "Despite the failure of Il21-/- and Il21r-/- mice to resolve their chronic infection, they did not succumb to a fulminating parasitemia within the 100–150 days of the study." (PMID 25763578, 2015). "In stark contrast, both Il21-/- and Il21r-/- mice failed to resolve the second infection and showed sustained high parasitemias." (PMID 25763578, 2015). "Similar to the P. chabaudi infection, both Il21-/- and Il21r-/- mice failed to clear a P. yoelii 17X(NL) erythrocytic infection, and developed sustained high parasitemias." (PMID 25763578, 2015). "Our findings suggest the importance of Tfh and IL-21 during chronic toxoplasmosis and establish a critical role for this cytokine in regulating CD8 T cell dysfunction by preventing the co-expression of multiple inhibitory receptors during chronic parasitic infection." (PMID 29163509, 2017). "Disruption of IL-21 signaling in B cells prevents the elimination of the parasite resulting in sustained high parasitemias, with no development of memory B-cells, lack of antigen-specific plasma cells and antibodies, and thus no protective immunity against a second challenge infection." (PMID 25763578, 2015). "Interestingly, neither Il21-/- nor Il21r-/- mice showed the peak of parasitemia characteristic of an acute primary infection after receiving the second P. chabaudi challenge, suggesting that some initial immune control could take place in the absence of an IgG B-cell response." (PMID 25763578, 2015).
Stroke (11 papers, 2014 to 2025). Sudden impairment of blood flow to a part of the brain due to occlusion or rupture of an artery to the brain. "TNFα, IL-17, and IL-21 have also have also been linked to stroke progression." (PMID 25309326, 2014). "Studies demonstrate that blocking γδ T cells, IL-17a, or IL-21 confers significant neuroprotective effects against ischemic brain injury in murine stroke models, establishing them as promising therapeutic targets for mitigating ischemic brain damage." (PMID 40746532, 2025). "To identify the population of T cells that produce IL-21 and contribute to stroke, we performed transient middle cerebral artery occlusion (tMCAO) in mice and performed flow cytometry on brain tissue." (PMID 35624463, 2022). "Our work is the first to identify a mechanism for how IL-21 producing T cells enter the ischemic brain and how these cells damage the inflamed tissue during the reperfusion phase of stroke." (PMID 35624463, 2022). "We also utilized immunohistochemistry in both mouse and human brain sections to identify cell types and inflammatory mediators related to stroke-induced IL-21 signaling." (PMID 35624463, 2022). "We found for the first time that total and phosphorylated/activated JAK3 are dramatically increased after stroke in the ipsilateral hemisphere (**P < 0.01; n = 5–13/group) in addition to increased IL-21 expression after stroke (**P < 0.01; n = 5–7/group)." (PMID 28790974, 2017). "This raised the possibility that understanding how IL-21 producing T cells enter the ischemic brain could reveal novel therapeutic approaches for stroke." (PMID 35624463, 2022). "Furthermore, following stroke, IL-21 and its receptor are expressed in the CNS via brain infiltrating CD4+ T cells, and CNS IL-21 strongly contributes to CNS tissue damage." (PMID 36256663, 2022). "A variety of researches have demonstrated that suppressing the infiltration of γδ T cells and reduction of IL-17a and IL-21 levels via either pharmacological or genetic tools could improve the outcome of stroke." (PMID 35432162, 2022). "In addition to increased IL-21 expression after stroke, we also found increased phosphorylated STAT3 which was decreased with decernotinib treatment." (PMID 28790974, 2017). "In addition, in postmortem human brain tissue, IL-21 was also found in the area surrounding acute stroke lesions, suggesting that IL-21-mediated brain injury may be relevant to human stroke." (PMID 35432162, 2022). "They exacerbate post‐stroke inflammation by producing inflammatory cytokines such as interferon (IFN)‐γ, interleukin (IL)‐21, tumor necrosis factor (TNF), and IL‐17." (PMID 38323746, 2024). "They contribute to the exacerbation of post-stroke inflammation by producing inflammatory cytokines like interferon (IFN)-gamma, interleukin (IL)-21, tumor necrosis factor (TNF), and IL-17." (PMID 38894965, 2024). "Furthermore, we analyzed the human stroke database GSE58294 and identified a positive correlation between the expression levels of P2X7 and IL-17A, as well as P2X7 and IL-21." (PMID 40948793, 2025). "Here, we show that CXCL13 is upregulated on inflamed vascular cells, and that during reperfusion, IL-21 producing CD4+ ICOS-1+ CXCR5+ TFH cells are recruited to the brain where they can induce caspase-mediated neuronal death and potentiate secondary stroke damage." (PMID 35624463, 2022). "Previously, we have found that IL-21 producing TFH cells affect post-stroke recovery but had not comprehensively defined their phenotype." (PMID 35624463, 2022). "IL-21 is known to regulate immune responses by promoting antibody production, T cell-mediated immunity, and NK cell and CD8+ T cell cytotoxicity; inhibiting IL-21 in experimental stroke correlated with improved behavioral outcome." (PMID 31440141, 2019).
Stroke (continued). "IL-21 activated the JAK/STAT pathway and induced apoptosis in primary ischemic neurons in mice under in vitro conditions, and inhibition of CXCL13 limited the migration and impact of these cells in the ischemic brain, thereby protecting mice from stroke injury." (PMID 38550918, 2024). "Finally, to evaluate cellular mechanisms of stroke, we exposed mouse primary neurons to oxygen glucose deprivation (OGD) conditions with or without IL-21 and measured cell viability, caspase activity and JAK/STAT signaling." (PMID 35624463, 2022).
ulcerative colitis (11 papers, 2010 to 2024). An inflammatory bowel disease involving the mucosal surface of the large intestine and rectum. "Additionally, identified within the human IBD ‘Immune effector module’, IL21 was over-expressed in ulcerative colitis and showed the highest abundance in the LPLs from H. hepaticus double-deficient Prdm1fl/fMaffl/fCd4Cre-infected mice, suggesting that IL-21 is associated with a type 1 response." (PMID 38609547, 2024). "It is implied that regulation of memory T cell differentiation through intervention with IL-7, IL-15, and IL-21 is an effective measure for the treatment of ulcerative colitis." (PMID 33597887, 2020). "Further, we observed downregulation of NF-κB and IL-21/IL-23 expression after CAR overexpression in a ulcerative colitis model." (PMID 30175139, 2018).
leukemia (10 papers, 2007 to 2024). A malignant (clonal) hematologic disorder, involving hematopoietic stem cells and characterized by the presence of primitive or atypical myeloid or lymphoid cells in the bone marrow and the blood. "To functionally investigate leukemia-initiating cells in vivo, we transferred BM cells from primary BL/6 and Il21−/− AML mice at titrated numbers into lethally irradiated secondary recipients." (PMID 39536753, 2024). "Transfer of CD4+ T cells into Il21−/− AML significantly reduced leukemia burden and L-GMP numbers and frequency to levels comparable to BL/6 AML mice." (PMID 39536753, 2024). "When transferred into mice with leukemia, IL-21-treated CARs had improved tumor control compared to those treated with IL-2 ex vivo." (PMID 30842774, 2019). "An ex vivo approach to utilize K562 leukemia targets with membrane bound IL-21 also appears promising." (PMID 25054077, 2014). "The mechanisms how IL-21 secretion and release are induced in patients with leukemia are currently unknown." (PMID 39536753, 2024). "In line with the findings obtained in Il21−/− AML mice, Il21R−/− AML mice had a lower expression of CD11b on bulk leukemia cells." (PMID 39536753, 2024). "To verify that the cellular processes and signaling cascades identified in Il21−/− AML mice are also modulated in Il21R−/− AML mice, we assessed CD11b expression on bulk leukemia cells as well as phosphorylation states of IKBα and p38-MAPK in L-GMPs from Il21R−/− and control Il21R+/−AML mice." (PMID 39536753, 2024). "Leukemia burden, as indicated by BM cellularity, numbers of MLL-AF9-GFP+Gr1+Cd11b+ leukemic cells in the spleen and BM, and leukemic blast frequency in the BM, was smaller in BL/6 AML mice compared to Il21−/− AML mice." (PMID 39536753, 2024). "In a phase 1/2 trial, 4 out of 4 leukemia patients who received WT1-specific CTL generated in the presence of IL-21 demonstrated both relapse-free survival without GvHD and did not need further anti-leukemic treatment." (PMID 35432319, 2022). "Using membrane-bound IL-21 on artificial antigen-presenting cells, NK cells can be expanded to large numbers to elicit graft vs. leukemia responses without inducing GVHD." (PMID 30842774, 2019). "Meguro and colleagues reported that the absence of IL-21 signal transmission reduced the effects of graft-versus-leukemia." (PMID 28627158, 2017). "These study data demonstrate that blockade of IL-21 signaling increases iTregs differentiation in vivo, but does not abrogate the graft versus leukemia (GVL) effect." (PMID 23843069, 2013).
renal cell carcinoma (10 papers, 2007 to 2024). "T cells from patients with renal cell carcinoma (RCC) exhibited multiple features of injury and depletion, as shown by the down-regulation of IL-21 expression associated with the dysfunction of CXCR5+ Tfh-like cells." (PMID 37355637, 2023). "In Phase I and IIa clinical trials, IL-21 was well tolerated and triggered moderate antitumor activity in some renal cell carcinoma (RCC) and metastatic melanoma (MM) patients." (PMID 22022259, 2011). "In clinical trials, recombinant human IL21 (rIL21) was administered to metastatic melanoma (MM) or renal cell carcinoma (RCC) patients at doses ranging between 1–300 μg/kg." (PMID 35323193, 2022).
gastric cancer (9 papers, 2013 to 2025). A primary or metastatic malignant neoplasm involving the stomach. "The serum concentration of IL-21 in patients with gastric cancer is significantly higher than that in controls, so the cytokine may play some role in the development and progression of gastric cancer." (PMID 34686626, 2021). "Our results showed that CLDN10 expression significantly correlated to the expression of B cells (CD19, CD79A) and Tfh cells (BCL6, IL21) markers, which indicated a potential mechanism for CLDN10 to regulate B cell function in gastric cancer." (PMID 34721537, 2021). "Another research discovered that circulating follicular helper T (cTfh) cells and their related factors (IL-21/CXCL13) may have a role in the development and progression of gastric cancer." (PMID 36793271, 2023). "GMF isolated from human gastric cancer and H. pylori infected tissues co-cultured with CD4+ T cells induced substantially higher levels of Th17 than GMF from normal tissues in an IL-6, TGF-β, and IL-21 dependent manner." (PMID 23365642, 2013). "Among them, INF-γ, IL-17 and IL-21, and B-cell inflammatory genes are significantly increased in people with CAD, and IL-17a promotes the epithelial to mesenchymal transition in gastric cancer cells through JAK2/STAT3, exacerbating the development of gastric cancer." (PMID 36970364, 2023). "IL-6 can impair Th1 differentiation through stimulating IL-4/IL-21 production and therefore has negative impacts on antitumor responses by shifting Th1/Th2 balance to Th2 dominance, leading to unfavorable prognosis in a wide range of tumor types including gastric cancer." (PMID 33144870, 2020).
Graves disease (9 papers, 2008 to 2024). Graves' disease is an autoimmune disorder that leads to overactivity of the thyroid gland (hyperthyroidism).It is caused by an abnormal immune system response that causes the thyroid gland to produce too much thyroid hormones. "The aim of the present case-control study was to investigate the genetic association between single nucleotide polymorphisms (SNPs) of rs907715 within the IL-21 gene and Graves’ disease (GD) in a Southern Chinese population." (PMID 24944624, 2014). "In this study, we investigated whether polymorphisms of the IL-21 and IL-21R are associated with Graves’ disease (GD) and Hashimoto’s thyroiditis (HT), two major forms of AITDs, among a Chinese population." (PMID 23889847, 2013). "IL-21 and IL-21R expression is upregulated in AITD, predominantly Graves' disease and Hashimoto's thyroiditis, and may be involved in the pathogenesis of AITD by enhancing the aberrant immune cascade, which indirectly affects thyroid function." (PMID 38022688, 2023).
liver cancer (9 papers, 2013 to 2025). An epithelial or non-epithelial malignant neoplasm that arises from the liver. "The mRNA and protein expression levels of GM-CSF, IL-21 and Rae-1 in spleen tissues decreased compared with the corresponding expression in liver cancer tissue in the Bio-CS/plasmid DNA and plasmid DNA groups (P < 0.01)." (PMID 28938619, 2017). "We also found that the survival rates of mice were highest in the IRES/combination group, which indicated that recombinant genes of GM-SCF, IL-21, and Rae-1 displayed the most effective treatment against liver cancer." (PMID 24350772, 2013). "In summary, GM-SCF, IL-21 and Rae-1 greatly inhibited the growth of liver cancer in a relevant mouse model." (PMID 24350772, 2013). "RT-PCR and Western blot assays were used to detect liver cancer tissues and to analyze the effect of GFP, GM-SCF, IL-21 and Rae-1 constructs and protein expression in liver cancer tissue." (PMID 24350772, 2013). "Previously, we studied recombinant plasmids that expressed both GM-CSF and IL-21 in a mouse model of orthotopic liver cancer by intravenous tail vein injection." (PMID 24350772, 2013). "Therefore, in this study, the combination of GM-SCF, IL-21 and Rae-1 collectively activated the murine immune system in liver cancer, and increased the numbers and cytotoxic activities of NK and CTL cells." (PMID 24350772, 2013). "A recombinant plasmid capable of co-expressing granulocyte-macrophage colony- stimulating factor (GM-SCF), interleukin-21 (IL-21), and retinoic acid early transcription factor-1 (Rae-1) was constructed, and its effects determined in a mouse model of subcutaneous liver cancer." (PMID 24350772, 2013). "IL21-armed CAR-T has been used in a clinical trial targeting several solid tumors expressing GPC3 antigen, including Liver Cancer, Rhabdomyosacoma, Malignant Rhabdoid Tumor, Liposarcoma, Wilms Tumor, and Yolk Sac Tumor (NCT04715191), but not ESCC." (PMID 40722671, 2025). "In this study, we treated liver cancer with a recombinant plasmid of GM-SCF, IL-21 and Rae-1 and found that the frequency of Tregs was significantly decreased as compared with treatment using a single gene." (PMID 24350772, 2013). "The recombinant plasmid (IRES/combination) used in this mouse model of subcutaneous liver cancer resulted in decreased tumor weights as compared mice that were transfected with IRES/GM-SCF-IL-21, IRES/GM-SCF and IRES/IL-21 treatment alone." (PMID 24350772, 2013). "In addition, IL-21 expression was closely related to HBV genotype, HBV clearance, HBeAg seroconversion, HBV related cirrhosis, liver failure, liver cancer and autoimmune dieases." (PMID 33287722, 2020).
liver fibrosis (9 papers, 2015 to 2022). "We identified an important cytokine IL-21 of Tfh cells which was closely related with hepatic fibrosis progression." (PMID 29192177, 2017). "We further delineated differences between IL-9 and IL-17 and their roles that played in liver fibrosis by using levels of IL-21 as an indicator." (PMID 26728971, 2016). "Importantly, this result was in consistence with the dynamics of IL-21+ cells in the progression of liver fibrosis." (PMID 29192177, 2017). "Our study contributes to better understand the immunopathogenesis of schistosomiasis and indicated that the IL-21 might be a potential therapeutic targeting factor for liver fibrosis in schistosomiasis." (PMID 29192177, 2017). "To further elucidate the contribution of IL-21 in the development of liver fibrosis in mice infected with S. japonicum, we primarily observed whether IL-21+ cells were expanded in liver egg granuloma." (PMID 29192177, 2017). "Furthermore, the relevance of these results showed that increased levels of IL-21 or IL-17A were positively correlated with liver fibrosis progression." (PMID 29192177, 2017). "Therefore, the elucidation of roles of Tfh cells and IL-21 may provide new insights into the immunopathology of liver fibrosis." (PMID 29192177, 2017). "In this context, the authors indicated that IL-17 levels (as a part of other secreted ILs as IL-6, IL-10, IL-21, IL-1β and INF-γ) increased in CHC and its level correlated directly with the degree of liver fibrosis." (PMID 35056005, 2022). "We further examined the role of the endogenous IL-9 in hepatic fibrosis and its relationship with other relevant cytokines, including IL-17A, IFN-γ, TGF-β1, IL-6, IL-4, IL-21 and TNF-α in response to hepatic fibrosis, by neutralizing IL-9 in a mouse model." (PMID 26728971, 2016). "Detection of the mRNA levels of a series of liver fibrosis-related molecules: Acta2, Col1a1, Tgfb1, and Timp1 in livers from IL-21−/−p40−/−IL-2Ra−/− mice and controls suggested no significant change of liver fibrosis." (PMID 35300072, 2022). "Notably, the numbers of IL21+ cells and IL21R+ cells were positively correlated with inflammation severity (r=0.45, P<0.05; r=0.43, P<0.05; respectively) and hepatic fibrosis stages (r=0.66, P<0.01; r=0.60, P<0.01; respectively) in PBC." (PMID 28425483, 2017). "However, whether IL-21, as other profibrogenic cytokines such as TGF-β1 and IL-13 characterized by Smad signaling pathway, plays an important role in the development of hepatic fibrosis is worthy of further research." (PMID 29192177, 2017). "However, neither the significance nor the role of IL-21 producing Tfh cell in the mediation of humoral immune response, to the exacerbation of hepatic fibrosis in mice infected with S. japonicum have been validated." (PMID 29192177, 2017).